RNU6-240P (RNA, U6 small nuclear 240, pseudogene)
Gene: Small nuclear RNA gene on chromosome 14 (73,659,564 to 73,659,660, reverse strand). Ensembl gene ENSG00000251907.
Homologues: Orthologues: chimpanzee U6 (100% identical), macaque U6 (93% identical). Paralogues in human: RNU6-86P (90% identical), RNU6-11P (89% identical), RNU6-15P (89% identical), RNU6-37P (89% identical), RNU6-43P (89% identical), RNU6-61P (89% identical), RNU6-10P (88% identical), RNU6-21P (88% identical), RNU6-25P (88% identical), RNU6-33P (88% identical), RNU6-41P (88% identical), RNU6-686P (88% identical), and 1285 more.